LIF (LIF interleukin 6 family cytokine)
Diseases named in the same sentence as LIF in open-access papers (continued):
Sharing a sentence is not in itself a finding about the gene and the disease.
tumor (continued). "Overexpression of LIF increases the abilities of migration and invasion in tumor cells in vitro and promotes tumor metastasis in vivo." (PMID 26716902, 2016). "Results from this study show that LIF induces the expression of miR-21 through the STAT3 signaling in human tumor cells." (PMID 26716902, 2016). "Taken together, results from this study revealed an important function and a novel underlying mechanism of LIF in EMT and tumor metastasis." (PMID 26716902, 2016). "Previous studies indicated IL6 and leukemia inhibitory factor (LIF) secretion increases in tumor tissues can promote TAM generation." (PMID 26790618, 2016). "Results from this study show that LIF promotes EMT of tumor cells, which is a new and important mechanism by which LIF promotes cancer metastasis." (PMID 26716902, 2016). "In summary, this study demonstrates that LIF promotes EMT, which is a novel mechanism by which LIF promotes tumor progression and metastasis." (PMID 26716902, 2016). "It is interesting to note that in our CCA series, LIF expression was more prevalent in the tumoral areas characterized by a ‘ductular-like’ appearance than by a ‘mucin-producing’ phenotype." (PMID 26296968, 2015). "On the other hand, LIF-mediated paracrine effects highlight the treatment-resistant functions exerted by the tumor reactive stroma in epithelial cancers with abundant desmoplasia." (PMID 26296968, 2015). "Here the authors show that the cytokine LIF initiates an epigenetic switch which results in the sustained invasive activity of the tumour cells." (PMID 26667266, 2015). "We further dissected the intracellular mechanisms underlying these effects and found that the leukemia inhibitory factor (LIF) plays a critical role in mediating these tumor suppressive effects." (PMID 25885043, 2015). "The continuous accumulation of HIF-2α under the hypoxic condition will lead to continuous induction of LIF in solid tumors with chronic hypoxic condition, which in turn can promote tumor development and progression." (PMID 25726527, 2015). "Recent studies including ours showed that LIF promotes tumor development and progression in many solid tumors through multiple mechanisms." (PMID 25726527, 2015). "Collectively, these reports and findings strongly suggest the important role of LIF in tumor development and progression." (PMID 25726527, 2015). "Overall these results demonstrate that LIF is not only involved in the tumor suppressive effects of TGFβ but also in its anti-metastatic activities, and that different pathways downstream of LIF are involved in these processes." (PMID 25885043, 2015). "Our previous studies indicate that, in MTC cells, this tumor suppressive signaling is connected to LIF-controlled extracellular mechanisms." (PMID 24662939, 2014). "Another interesting finding was the over-expression of LIF in tumor, whose receptor LIFR was over-expressed in adjacent mucosa but not in the tumor." (PMID 24597571, 2014). "Our initial xenotransplantation studies using leukemia inhibitory factor (LIF) treated undifferentiated MPeMSCs showed an early tumor induction in mice proving that MPeMSCs are tumorigenic." (PMID 23285196, 2012). "IL-1β/TGF-β-induced neurospheres display up-regulated expression of stemness factor genes (nestin, Bmi-1, Notch-2 and LIF), and increased invasiveness, drug resistance and tumor growth in vivo: hallmarks of GSCs." (PMID 22330721, 2012). "Many human tumor samples also gained expression of a coordinately regulated module associated with advanced malignancy (ABCC1, FOXO3A, LIF, PIK3R1, PRNP, TNC, TIMP3 and VEGF)." (PMID 17615082, 2007). "Collectively, these findings demonstrate that LIF is a critical mediator of tumor progression and immunosuppression in peritoneal carcinomatosis and may serve as a therapeutic target and prognostic biomarker in this aggressive GC subset." (PMID 41163398, 2025).
tumor (continued). "While EC359 alone did not impair basal proliferation, it attenuated LIF‐driven oncogenic activity, suggesting that LIFR blockade may be a viable strategy to counteract LIF‐mediated tumor progression in GC." (PMID 41163398, 2025). "Furthermore, MSC‐1/AZD0171 neutralizing LIF mAb promotes anti‐tumor inflammation and slows tumor growth by modulating TAM and inhibiting cancer stem cells." (PMID 40416597, 2025). "Whether a similar mechanism, where LIF regulates glycolysis in tumor cells, exists in PDAC remains to be elucidated, as we observed a downregulation of glycolysis following treatment." (PMID 39857986, 2025). "Additionally, LIF and LIFR expression levels are higher in GC cells compared to normal tissue and have been linked with tumor differentiation, increased lymph node metastasis, and higher rates of lymphovascular invasion." (PMID 41163398, 2025). "The findings demonstrated a strong correlation between H. pylori bacterial load, LIF expression, and IL‐11 expression, suggesting that persistent H. pylori infection drives an inflammatory cascade that may contribute to tumor progression." (PMID 41163398, 2025). "Notably, the combination of anti‐LIF and anti‐PD‐L1 therapy led to tumor regression in 80% of treated mice, with a subset exhibiting complete tumor clearance." (PMID 41163398, 2025). "LIF gene expression correlated with immune cells (e.g., neutrophils), age, and tumor grade." (PMID 41163398, 2025). "However, both chemo+anti-PD-L1 and chemo+anti-LIF+anti-PD-L1 treatments significantly reduced tumor growth compared to untreated controls." (PMID 39857986, 2025). "More recently, our previous study demonstrated that the natural compound solamargine could slow HCC tumor progression by inhibiting the LIF/miR‐1/Akt signaling pathways and thereby triggering apoptosis and autophagy." (PMID 40416597, 2025). "Importantly, combining LIF inhibition with PD‐1 checkpoint blockade in murine models demonstrated enhanced tumor regression." (PMID 41163398, 2025). "In addition, CAFs promote tumor growth and invasion by secreting several cytokines, exosomes, and growth factors, such as leukemia inhibitory factor (LIF) and growth differentiation factor 15 (GDF15)." (PMID 40686923, 2025). "Importantly, neutralizing extracellular LIF with anti‐LIF antibodies restored chemosensitivity, reduced colony formation, and inhibited tumor growth when treated with cisplatin, emphasizing the paracrine function of LIF in chemoresistance." (PMID 41163398, 2025). "Additionally, leukemia inhibitory factor (LIF) has been identified as another significant tumor‐derived cytokine." (PMID 39764565, 2025). "Second, anti-LIF repolarized monocytes and macrophages toward an anti-tumor phenotype." (PMID 39857986, 2025). "The combination treatment of chemotherapy, anti-LIF, and anti-PD-L1 led to an increase in M1 macrophages and a reduction in M2 macrophages, accompanied by enhanced interferon response pathways, suggesting a shift towards an anti-tumor phenotype." (PMID 39857986, 2025). "Moreover, they have the abilities to limit tumor growth by releasing proinflammatory cytokines, leukemia inhibitory factor (LIF) and granulocyte-macrophage colony-stimulating factor (GM-SCF)." (PMID 40136652, 2025). "Notably, tumor control was markedly improved in the chemo/anti-LIF/anti-PD-L1 group compared to the chemo/anti-PD-L1 group." (PMID 39857986, 2025). "Additionally, since LIF is released both in a paracrine and endocrine manner but is also generated by tumor-infiltrating macrophages (TAM), our results highlight a further mechanism by which oncogenic macrophages regulates cancer cells growth." (PMID 37945798, 2024). "This is in good agreement with the results of this work, where animals from the “LLC_Gr_HCA” group showed a decrease in the IL-6 levels and an increase in the percentage of animals with undetectable LIF levels, along with a decrease in the tumor size and metastasis." (PMID 38891915, 2024).
tumor (continued). "For example, TAMs are known to express leukemia inhibitory factor (LIF), which promotes tumor progression, inflammation, and therapeutic resistance by creating an immunosuppressive TME by inducing the differentiation of Tregs and enhancing the production of other immunosuppressive cytokines." (PMID 39335494, 2024). "Additionally, we also found that the levels of LIF were significantly correlated with age and tumor grade staging." (PMID 38490994, 2024). "In cancer, LIF expression has been reported in many solid tumors, such as colorectal, nasopharyngeal, skin, and breast cancer, and has been reported to support a variety of tumor functions." (PMID 38443597, 2024). "However, we observed that the tumor signals to the host to downregulate the production of LIF as it grows." (PMID 39451257, 2024). "Concurrently, LIF, an entity influential across various physiological and pathological scenarios—especially in mediating inflammatory responses—has previously been indicted as a pro-tumor agent in certain neoplasms." (PMID 38490994, 2024). "Currently, it remains unknown whether the autocrine LIF/LIFR loop, other tumor intrinsic, as well as external effects of the LIF/LIFR axis drive the progression of OCa." (PMID 38789520, 2024). "The role of LIF/LIFR autocrine signaling in tumor recurrence is substantial since following chemotherapy, residual CSCs might repopulate tumor once again utilizing positive autocrine loop without the need of paracrine factors from the host tissue." (PMID 38789520, 2024). "Meanwhile, reminiscent of that observed in the tumor-bearing mice, this LIF treatment did not cause detectable neural activities in the NTS or PBN-L/-R." (PMID 38467743, 2024). "LIF plays an interesting but complex role in tumor development and progression." (PMID 39451257, 2024). "It was demonstrated that the leukemia inhibitory factor (LIF) belonging to the IL-6 family of cytokines provided a pro-dormancy signal to tumor cells, with dormant cancer cells being LIF-responsive, compared to colonizing metastatic cells that did not respond to LIF." (PMID 38418814, 2024). "However, it came to our attention that the intraperitoneal administration of 1 μg recombinant LIF protein resulted in plasma levels of ~50 ng/mL, which would be 100-fold higher than those in the tumor-bearing mice." (PMID 38467743, 2024). "The critical roles of LIF in tumorigenesis and tumor progression have been highlighted." (PMID 39169307, 2024). "We managed to find that while the intraperitoneal injection of 5 μg galectin-3 (Gal3) alone only induced neural activities in the Ve-L/-R of non-tumor-bearing mice, it acted in a cooperative manner with 2 ng LIF to trigger responses of all the signature brain regions." (PMID 38467743, 2024). "In our study, we found 1G11 blocked the LIF/LIFR/STAT3 axis in tumor cells in vitro." (PMID 39169307, 2024). "Moreover, we showed that pharmacologic or genetic blockage of cancer cell-derived LIF or Gal3 signaling to the brain would strongly inhibit tumor progression." (PMID 38467743, 2024). "We observed a downregulation of LIF production in all mice when the tumor began to grow." (PMID 39451257, 2024). "Recent advancements in understanding the pathophysiology of cancer cachexia have identified potential therapeutic targets, including tumor-derived mediators such as leukemia inhibitory factor (LIF), zinc alpha glycoprotein (ZAG), activin A, and growth differentiation factor 15 (GDF-15)." (PMID 39727925, 2024). "In conclusion, LIF could promote the recruitment of neutrophils and the formation of NETs in the tumor microenvironment of GC." (PMID 38490994, 2024). "This study intricately explores the role of the TGFβ-Smad-LIF axis within the tumor microenvironment in propagating peritoneal metastasis, with a specific emphasis on its molecular mechanism in instigating Neutrophil Extracellular Traps (NETs) formation and encouraging GC cellular functions." (PMID 38490994, 2024).
tumor (continued). "The AU-rich element RNA-binding protein AUF1 stimulated circ_0010467 to promote platinum resistance through inducing tumor cell stemness, while circ_0010467 acted as a miR-637 sponge to activate the leukemia inhibitory factor (LIF) in the miR-637/LIF/STAT3 axis." (PMID 39452837, 2024). "LIF was mainly expressed in tumor cells and increased in advanced tumors." (PMID 37360193, 2023). "The TNF-α targets downregulated by Ent include LIF, a pro-tumorigenic cytokine that triggers tumor STAT3 pathway and contributes to PDAC progression and therapeutic resistance, indicating the potential of HDACi to reduce the pro-tumorigenicity of CAF secretome." (PMID 38057326, 2023). "Particularly, we found that TM4SF1 and LIF might serve as tumor progression markers in patients with CRC." (PMID 37360193, 2023). "The analysis of tumor databases has uncovered a correlation between diminished survival rates and increased expression of leukemia inhibitory factor (LIF), suggesting a potential connection between altered LIF expression and unfavorable overall survival in Type II ECa." (PMID 38139260, 2023). "To investigate whether LIF expression in human cancer correlates with local stromal populations, we analyzed RNA-sequencing data from public human tumor datasets." (PMID 37134077, 2023). "Future studies will determine whether antagonizing LIF or IL-1 or both is sufficient to reduce tumor progression either in the murine model or in humans." (PMID 37141182, 2023). "LIF is secreted at varying levels by the selected GC cell lines without any specific features associated with the tumor type." (PMID 38137514, 2023). "However, similar functions of LIF have been described in chodorma (a rare tumor of spine and skull), in pancreatic tumors and in head and neck and lung carcinomas." (PMID 38137514, 2023). "Future studies will be necessary to define the functional significance and underlying mechanisms of other tumor supportive cytokines/chemokines (i.e., IL1A/B, LIF, G/M-CSF and CXCL2/3) and inflammatory proteins (i.e., S100P and S100A9) in mediating XIST regulation of tumor growth and CSC activity." (PMID 36922677, 2023). "Together, these data warrant future studies addressing whether disruption of the local IL-1α/TNFα axis can impede EMH and how cell products of EMH induced by IL-1α and LIF impact the tumor microenvironment and cancer outcomes." (PMID 37134077, 2023). "LIF also plays a pro-oncogenic role in tumor progression, accompanied by poor prognosis." (PMID 37103052, 2023). "Our data suggest that LIF produced by tumor expands distal stromal components in mouse models." (PMID 37134077, 2023). "The tumor secreted LIF promotes CAF activation and the expression of LIF in fibroblasts." (PMID 36980785, 2023). "Together, these data suggest that ABS cells form an expandable niche in the spleen in direct response to tumor-derived LIF and that this cancer-stromal interaction may operate in human tumors as well." (PMID 37134077, 2023). "The capacity of Ent to repress LIF expression prompted an investigation of whether HDACi reduces the tumor promoting activities of CAFs through modulating paracrine signaling." (PMID 38057326, 2023). "The concentration of LIF secreted by each tumor, determined by ELISA test, is also presented." (PMID 38137514, 2023). "This study shows that tumor-produced IL-1α and LIF promote extramedullary hematopoiesis." (PMID 37134077, 2023). "In addition, lower abundance of intratumoral LIF was also detected in the transplants with HDAC-deficient CAFs, consistent with reduced tumor promotion by these CAFs." (PMID 38057326, 2023). "Interestingly, the rise of LIF in tumor microenvironment would be due to the presence of transforming growth factor β (TGF-β) that induces LIF production in both stroma and parenchyma cells." (PMID 35163731, 2022).
tumor (continued). "At the same time, LIF was reversed to promote tumor formation and metastasis." (PMID 35992780, 2022). "Solamargine initiated the repolarization of M2-like towards M1-like phenotype via decreasing the expression of leukemia inhibitory factor (LIF) derived from tumor cells, an immunosuppressive mediator that activated the STAT3 signaling to alter the differentiation of immune cells." (PMID 36615387, 2022). "Given this, targeted LIF may reduce tumor progression and the development of late-stage malignancy, allowing patients to have a better quality of life." (PMID 35740622, 2022). "A long list of tumor-borne, often proinflammatory factors, including interleukin-6 (IL-6), parathyroid hormone–related protein (PTHrP), leukemia inhibitory factor (LIF), zinc α-glycoprotein, or growth differentiation factor-15 (GDF-15), trigger CAC in mouse models." (PMID 35210363, 2022). "Solamargine at low doses regulates the biological function of immune cells by inhibiting the LIF/Stat3 signaling pathway, reshaping the tumor microenvironment, and inhibiting the process of tumor cell heterogeneity, thereby exerting a synergistic antitumor effect." (PMID 36052142, 2022). "Here, we investigated whether the promoting effect of LIF on glucose uptake and glycolysis contributes to the tumor-promoting function of LIF." (PMID 35440095, 2022). "We speculate that LIF can promote adipocyte dedifferentiation in the tumor microenvironment and in the case of cachectic adipocytes." (PMID 35740622, 2022). "EEC tumor patients with a high BMI exhibited elevated levels of LIF expression." (PMID 36358818, 2022). "It has been shown that abnormally high LIF expression in the tumor microenvironment can promote macrophage aggregation, which could secrete IL6 and IL-1α to induce muscle atrophy and cachexia." (PMID 35740622, 2022). "Tumor-derived LIF can promote the malignant behavior of tumors in an autocrine manner." (PMID 35740622, 2022). "Tumor growth can lead to hypoxic “pockets” of cells, and it has been hypothesized that the hypoxic cells may secrete LIF to stimulate angiogenesis." (PMID 35204717, 2022). "Furthermore, JAK inhibition has been shown to reduce cancer cell proliferation and tumour growth in vitro by suppressing IL1-induced LIF signalling in iCAFs." (PMID 36358721, 2022). "In addition, tumor-derived interleukin 1 alpha (IL1A) induces LIF upregulation in PSCs, leading to the activation of JAK-STAT signaling pathways to promote iCAF induction." (PMID 35805064, 2022). "However, some research has not detected the elevated expression of IL-6 accompanied by the over-expression of LIF secreted by the tumor in animal models." (PMID 35740622, 2022). "Furthermore, it was proven that increases in the levels of IL-6 and G-CSF are dependent on tumor-derived LIF." (PMID 33557173, 2021). "This was also consistent with earlier studies that had shown LIF is secreted by PSCs, drives tumor progression and may be a useful therapeutic target in patients with PDAC." (PMID 33868174, 2021). "The LIF amount secreted by a tumor seems to regulate cancer genesis." (PMID 34295890, 2021). "Moreover, in PC models, STAT3 activity in tumor-infiltrating MDSCs correlated with increased PD-L1 levels and elevated plasma levels of IL6-type cytokines (such as LIF), suggesting a potential cross-talk mechanism promoting tumor immune evasion." (PMID 34830209, 2021). "Furthermore, in vitro (in C2C12 myotubes) and in vivo (in LLC tumor-bearing mice) experiments were performed to explore the mechanisms of miR-29c and LIF in lung cachexia." (PMID 34838029, 2021). "Clearly, the activation of secretory autophagy in tumor and stromal cells results in the release in the extracellular space of a number of factors, including inflammatory cytokines and chemokines (e.g., interleukin 1β, CXCL8, LIF), thus impacting on the tumor microenvironment." (PMID 34944948, 2021).